TLR4 (toll like receptor 4)
Diseases named in the same sentence as TLR4 in open-access papers (continued):
Sharing a sentence is not in itself a finding about the gene and the disease.
atherosclerosis (continued). "Of particular importance is the role of GPER1 in immune cells, particularly in the antagonism of TLR4-dependent pro-inflammatory pathways, which also highlights, perhaps, a central role of NFκB-dependent signaling in pro-inflammatory vascular disease and atherosclerosis progression in particular." (PMID 34746830, 2021). "This study showed that SIS could significantly increase the risk of atherosclerosis through HPA-axis, TLR4 up-regulation on circulating monocytes, increased in arterial inflammation, increased in the gene expression of cell adhesion molecules, and finally M1 macrophage polarization in the intima." (PMID 34580342, 2021). "Thus, we attempted to find a new therapeutic drug for atherosclerosis by reducing TLR4 signaling." (PMID 32849545, 2020). "In addition, associations between TLR4 polymorphisms and susceptibility for atherosclerosis have not been previously investigated in CKD patients of African ancestry." (PMID 32649699, 2020). "The molecular mechanism of atherosclerosis progressions has been studied for decades, and multiple pathways and physiopathological processes are involved in the development of atherosclerosis, such as inflammation, apoptosis, and necrosis as well as NF-κB pathways and TLR4/MAPK pathways." (PMID 31354385, 2019). "Similarly, the regulation of NOV might play a bridging role in inflammatory response and lipid accumulation in macrophages during atherogenesis as both toll-like receptor 4 and IFNγ-signaling represent major regulators in atherosclerosis." (PMID 31921150, 2019). "However, it should be definitely shown whether the cooperation between TLR‐4 signalling and impaired lipid metabolism in HSPCs can contribute to the predominant differentiation of HSPCs to the myeloid lineage in atherosclerosis." (PMID 29364567, 2018). "Analysis of the Southampton Atherosclerosis Study, on the other hand, could not show any association between the TLR-4 Asp299Gly polymorphism and either severity of or susceptibility to coronary artery diseases." (PMID 29367560, 2016). "Indeed, TLR4 blockade arises as potential therapy against many manifestations of transplant and CNI-associated vascular disease, including inflammation, hypertension and atherosclerosis." (PMID 27295076, 2016). "However, TLR4/NF-κB signaling whether directly contributes to the development of atherosclerosis in CUMS mice is unclear." (PMID 25860573, 2015). "Therefore, knockdown TLR4 expression attenuated CUMS-induced atherosclerosis maybe though lowering the downstream inflammatory cytokines expression in apoE-/- mice." (PMID 25860573, 2015). "CUMS response may activate TLR4, thereby increasing proinflammatory cytokines release through the NF-κB pathway to promote inflammation response, thus contributing to the development of atherosclerosis." (PMID 25860573, 2015). "However, other researchers reported that TLR-4 polymorphism is not significant in relation to atherosclerosis and other coronary diseases." (PMID 25329057, 2014). "Hence, these results suggested that miR-21 could negatively regulated lipid accumulation via TLR4-NF-κB pathway in LPS-stimulated macrophages, implying an important role in the development of atherosclerosis." (PMID 24502419, 2014). "Thus, it is suggested that TLR4 signaling in monocyte might be a major contributor in the initiation of atherosclerosis." (PMID 25116953, 2014). "However, we have demonstrated TLR4 antagonism exacerbates atherosclerosis progression." (PMID 25010102, 2014). "Additionally, lack of TLR4 reduces atherosclerosis and alters plaque phenotype in apoE-deficient mice fed a high-cholesterol diet." (PMID 24918924, 2014).
atherosclerosis (continued). "Indeed, there is further evidence to support the hypothesis that TLR4 signaling is relevant to atherosclerosis and lupus lung injury." (PMID 24324506, 2013). "However, the authors found no role for TLR4-deficient bone marrow-derived cells in the development of atherosclerosis in this model." (PMID 24376657, 2013). "Indeed TLR4 may play a pivotal role in the early stages of atherosclerosis since it is upregulated on endothelial cell by low shear stress and oxidized lipoproteins." (PMID 17534423, 2007). "The innate immune response is activated through Toll-like receptor 4 (TLR4) when LPS levels increase, thus promoting vascular inflammation and atherosclerosis by elevating inflammatory cytokines interleukin-6 (IL-6) and IL-8." (PMID 40421334, 2025). "It has also been reported that disruption of toll-like receptor 4 (TLR4)/EGFR signaling pathway reduced inflammatory activity and foam cell formation, resulting in alleviating atherosclerosis." (PMID 40478326, 2025). "The key factors contributing to the onset and progression of atherosclerosis include the pro-inflammatory cytokines interferon (IFN)α and IFNγ and the pattern recognition receptor (PRR) Toll-like receptor 4 (TLR4)." (PMID 39840103, 2024). "Herein, we presented the current evidence on the structure, functions, and roles of TLR4, PCSK9, and LOX-1 in atherosclerosis." (PMID 38445291, 2024). "Many TLR family members such as TLR1, TLR2, TLR4, and TLR5 that are detected in human plaque and atherosclerosis mouse models are mainly expressed by macrophages and ECs." (PMID 39399488, 2024). "In conjunction with TLR4, Olfr2 expressed in mouse vascular macrophages can active NLRP3 inflammasome to promote the development of atherosclerosis." (PMID 38803504, 2024). "The key factors contributing to the early stages of atherosclerosis and plaque development include the pro-inflammatory cytokine interferon (IFN)α and IFNγ and the pattern recognition receptor (PRR) Toll-like receptor 4 (TLR4)." (PMID 39840103, 2024). "The Toll-like receptor 4 (TLR4)/Nuclear factor-κB (NF-κB) pathway participates in oxidative stress and induces atherosclerosis in ApoE−/− mice by up-regulating inflammatory cytokines." (PMID 38026969, 2023). "TLR4 belongs to the TLR family and is considered as a linking molecule between the gut microbiota, endotoxemia and atherosclerosis." (PMID 38041095, 2023). "Therefore, we hypothesized that lycopene could effectively protect gut microbiota dysbiosis induced by the high-fat diet, reduce intestinal permeability and blood LPS levels, thereby inhibiting cardiovascular TLR4/NF-κB signal cascade and preventing the progression of atherosclerosis." (PMID 38041095, 2023). "In turn, it has been reported that activation of some TLRs such as TLR2 and TLR4, leads to the transcription of adhesion molecules such as VCAM and ICAM in a process mediated by NF-κB, facilitating atherosclerosis progression." (PMID 37175608, 2023). "Recent studies indicate that the TLR4/MyD88/NLRP3 pyroptosis signaling pathway plays a key role in the occurrence and development of cancer, heart failure, and atherosclerosis." (PMID 36733418, 2023). "SIRT1 activation by resveratrol inhibits the TLR4-mediated inflammatory response in ox-LDL-activated platelets, thus likely contributing to the treatment of thrombosis and atherosclerosis." (PMID 38304233, 2023). "Indeed, in atherosclerosis, diverse proinflammatory pathways are hyperactivated (e.g., TLR4/NF-κβ) and cytokines are chronically overexpressed, which may amplify the immune-mediated response to the SARS-CoV-2, increasing the susceptibility to a cytokine storm, and plaque rupture and thrombosis." (PMID 35333112, 2022).
atherosclerosis (continued). "Atherosclerosis is a multifactorial disease with different stages of inflammation from initiation to progression, and toll-like receptors (TLRs), notably TLR2 and TLR4, are involved in developing the atherosclerotic disease." (PMID 35928361, 2022). "TLR4 is a member of the Toll-like receptor (TLR) family and is involved in the progression of atherosclerosis, including monocyte activation, endothelial cell injury, vascular smooth muscle cell fibrosis, and macrophage and foam cell production." (PMID 36204316, 2022). "Taken together, these findings suggested that TLR4 and CBS play key roles in the development of atherosclerosis." (PMID 36204316, 2022). "The eight major genes upregulated in the carotid vessels (IL18, PDGFRA, IL17, LOX1, TLR4, MYF5, IL1B, and PDPN) were intimately involved in the pathologic progression of atherosclerosis and NIH." (PMID 35531433, 2022). "TLR4 knockout mice are resistant to HFD-induced glucose intolerance as well as HFD-induced atherosclerosis." (PMID 34299233, 2021). "Cigarette smoke significantly enhanced the expression of TLR2/TLR4 mRNA in histamine and lipopolysaccharide (LPS) treated cells, which suggested that upregulation of TLR2/TLR4 signaling promoted progression of atherosclerosis." (PMID 33995400, 2021). "Nevertheless, calprotectin advances ROS generation binds to the toll-like receptor 4 and receptor for advanced glycation and products (RAGE), important signaling pathways involved in the pathogenesis of atherosclerosis." (PMID 34886800, 2021). "For example, in the case of lipid profile, evaluation of TLR4 level, ox-LDL, and MDA can be helpful for the differentiation of TAO and atherosclerosis." (PMID 34679434, 2021). "These mediators damage human coronary smooth muscle cells and increase atherosclerosis which was found to be TLR2- and TLR4-dependent." (PMID 33679711, 2020). "Toll-like receptors can initiate inflammatory responses in atherosclerosis and STAT-1 is involved in the signaling pathways mediated by toll-like receptor 4, resulting in increased expression of several pro-inflammatory and pro-atherogenic mediators." (PMID 33287461, 2020). "Our results revealed that HMGB1 is a critical signal for TLR4-mediated the down-regulation of PPARγ/LXRα-ABCA1, which accelerates CUMS-induced atherosclerosis." (PMID 30881312, 2019). "In this study, CUMS ApoE-/- mice model with atherosclerosis was established, and HMGB1 inhibitor or TLR4 inhibitor was used to test its role in atherosclerosis under CUMS." (PMID 30881312, 2019). "Blocking HMGB1 release by EP or inhibiting TLR4 activation by TAK-242 almost reversed CUMS-induced the drownregulation of PPARγ-LXRα-ABCA1 and impeded the development of atherosclerosis in apoE-/- mice." (PMID 30881312, 2019). "For instance, TLR4 knockout mice reduce autoantibody production and vasculature inflammation in systemic lupus erythematosus (SLE) and atherosclerosis, respectively." (PMID 30877182, 2019). "In atherosclerosis and other pathological conditions, CD36 and Toll-like Receptor-4 (TLR4), along with TLR6, act together in lipid uptake and inflammatory behavior." (PMID 31736973, 2019). "Interestingly, even though TLR4 deficiency reduced atherosclerosis extent, the lack of MyD88, an adaptor protein in the TLR signaling cascade, further reduced it, possibly because it participates in the signal-transduction pathway of the receptors for IL-1β and IL-18." (PMID 30558209, 2018). "Key factors contributing to onset and progression of atherosclerosis include the pro-inflammatory cytokines Interferon (IFN)α and IFNγ and the Pattern Recognition Receptor (PRR) Toll-like receptor 4 (TLR4)." (PMID 30283459, 2018). "Toll-like receptor 4, NF-κB, and JAK/STAT are atherosclerosis-related inflammatory signaling pathways." (PMID 30142970, 2018).
atherosclerosis (continued). "OxLDL has been shown to induce Cxcl1 expression in macrophages via a co-operation of CD36/TLR4/TLR6, and CXCL1 represents a key mediator of leukocyte recruitment in atherosclerosis." (PMID 26947073, 2016). "This review outlines the pathophysiological role of TLR2, TLR4, and TLR9 in atherosclerosis, focusing on evidence from animal models of the disease." (PMID 27795867, 2016). "This review article aims to describe the immunological role of TLRs in promoting the development of atherosclerosis, with a primary focus on the function of TLR2, TLR4, and TLR9." (PMID 27795867, 2016). "Previous studies showed that activated TLR4/MyD88 upregulated NOX4 expression in LPS-activated cells and lead to atherosclerosis." (PMID 27891092, 2016). "Given the role of TLR4 in inflammation and in regulating VSMC phenotypic modulation, it is important to uncover the precise mechanism by which TLR4 regulates VSMC function and atherosclerosis." (PMID 27563891, 2016). "The subsequent sections of this review focus on the roles of TLR2, TLR4, and TLR9 in the pathogenesis of atherosclerosis." (PMID 27795867, 2016). "Key factors contributing to early stages of atherosclerosis and plaque development include the pro-inflammatory cytokines Interferon (IFN)α, IFNγ and Interleukin (IL)-6 and Toll-like receptor 4 (TLR4) stimuli." (PMID 27166190, 2016). "Most studies hitherto have focused on the implications of TLR4 or TLR2 on atherosclerosis, while the data on the roles of TLR9 in atherosclerosis is scarce." (PMID 26257462, 2015). "There is compelling evidence that apolipoprotein E deficiency (ApoE−/−) combined with a high-fat diet regulates toll-like receptor 4 (TLR4) expression and promotes atherosclerosis development." (PMID 25975841, 2015). "Pg injection herein significantly increased local aortic expressions of TLR-2 and TLR-4, indicating that Pg stimulated systemic inflammatory immune response through TLR-2 and TLR-4, finally leading to atherosclerosis." (PMID 26063970, 2015). "Our study provides evidence to suggest that in ECs and VSMCs STAT1 orchestrates a platform for cross-talk between IFNγ and TLR4, and identifies a STAT1-dependent gene signature that reflects a pro-atherogenic state in human atherosclerosis." (PMID 25478796, 2014). "A role for TLRs in high-fat-diet-induced atherosclerosis in animal models has been shown in studies using ApoE-/- TLR2-/- and ApoE-/- TLR4-/- mice." (PMID 25540039, 2014). "We now know the innate immune receptors, TLR4 and TLR2, intrinsically regulate atherosclerosis in animal models and induce inflammatory responses in human vascular cells." (PMID 24690886, 2014). "Toll-like receptor 4 (TLR4) are important in inflammation and regulating vascular smooth muscle cells (VSMCs) proliferation, which are related to atherosclerosis and restenosis." (PMID 24667766, 2014). "Collectively, the results from these studies and our present findings strongly suggest that enhanced signaling through TLR4 and ERK, in inflammatory cells (monocytes/macrophages), plays an important role in the pathogenesis of atherosclerosis." (PMID 23671849, 2013). "During atherosclerosis, these mechanisms can be detrimental, as seen by the activation of TLR2 and TLR4." (PMID 23880853, 2013). "Human and mouse atherosclerosis is characterised by an increased expression of TLR1, TLR2 and TLR4 (and to some extent TLR5), mainly by macrophages and endothelial cells." (PMID 21526997, 2011). "The circulating monocytes of ApoE-/- mice with advanced atherosclerosis have increased TLR2 and TLR4 expression." (PMID 21526997, 2011). "TLRs are differentially expressed by the various cell types in atherosclerosis, with TLR2 and TLR4 found on monocytes, macrophages, foam cells and myeloid DCs, as well as smooth muscle cells and B lymphocytes." (PMID 21526997, 2011).
atherosclerosis (continued). "It has been shown to inhibit the TLR4/NF‐κB/NLRP3 pathway, a key receptor in the Toll‐like receptor family that mediates LPS‐stimulated tissue damage, apoptosis, and inflammation, thus protecting VECs and preventing thrombosis and atherosclerosis progression." (PMID 40634132, 2025). "Conversely, the expression of TLR2 and TLR4 on monocytes (both increased during the development of atherosclerosis) was reduced in the patient’s non-classical monocyte fractions; however, this has been reported before in patients with chronic inflammation." (PMID 40149441, 2025). "Loss of Ash2l abundance at the promoter of PPARγ inhibited CD36 transcription, which significantly weakened the proximity ligation signals between TLR4 and CD36, thus reducing NF-κB signal activation and contributing to the protection against endothelial injury and atherosclerosis." (PMID 38280036, 2024). "TLR4, LOX-1, and PCSK9 have distinctive roles in atherosclerosis development." (PMID 38445291, 2024). "Curcumin has also been shown to protect against atherosclerosis in mice lacking apolipoprotein E by inhibiting Toll-like receptor 4 expression, in addition to its ability to suppress cholesterol accumulation in macrophage foam cells and atherosclerosis." (PMID 37241765, 2023). "Here, based on in vitro evidence that SAA1 promotes atherosclerosis, we further confirm that such function of SAA1 may depend on activation of the TLR4-related NF-κB signaling pathway." (PMID 36158875, 2022). "The effects of TREM-1 and TLR-4 inhibition on early vessel thrombosis was under investigation because pro-inflammatory mediators TREM-1 and TLR-4 play a critical role in atheromatous plaque formation, atherosclerosis, and vessel stenosis." (PMID 35203642, 2022). "Although the exact mechanism has not been fully elucidated, the HMGB1/TLR4/MyD88 signaling pathway appears to be a new target for SLE combined with atherosclerosis treatment." (PMID 35571092, 2022). "Calprotectin is a member of endogenous danger-associated molecular patterns (DAMPs) that promote in?ammation through activating toll-like receptor-4 (TLR4) and the receptor for advanced glycation end products (RAGE), which play pivotal roles in the development and progression of atherosclerosis." (PMID 35386415, 2022). "What is more, the knockdown of lncRNA XIST could reduce the vascular wall injury induced by low-density lipoprotein via miR-204-5p/toll-like receptor 4 (TLR4), which attenuated atherosclerosis." (PMID 36474713, 2022). "In atherosclerosis, lipoproteins trigger TLR2 and TLR4 signalling pathways." (PMID 35017526, 2022). "Studies have found that a heterodimer of TLR4 and TLR6 promote a protracted sterile inflammatory response after being triggered by oxidized low-density lipoprotein (LDL) and β-amyloid, which involves the pathogenesis of atherosclerosis and Alzheimer’s disease." (PMID 35126357, 2021). "On the other hand, it has been determined that there is a reduction in neointimal formation in the ‘early’ stages of atherosclerosis in the absence of TLR4 signaling." (PMID 32378144, 2021). "Besides, another metabolite, LPS, involved in infectious diseases has recently shown to have some effects on atherosclerosis based on in experimental and clinical trials by binding to various proteins, such as LBP, CD14, TLR-4, and MD-2." (PMID 34414217, 2021). "In a recent study, TLR4 antagonist, Rhodobacter globosa lipopolysaccharide (RS-LPS), did not alleviate the early atherosclerosis process in ApoE−/− mice." (PMID 32002588, 2020).